KRTAP4-8 (keratin associated protein 4-8)
Description:
In the hair cortex, hair keratin intermediate filaments are embedded in an interfilamentous matrix, consisting of hair keratin-associated proteins (KRTAP), which are essential for the formation of a rigid and resistant hair shaft through their extensive disulfide bond cross-linking with abundant cysteine residues of hair keratins. The matrix proteins include the high-sulfur and high-glycine-tyrosine keratins.
Synonyms: KAP4.8; KRTAP4.8
Tractability: No criterion of Open Targets' tractability assessment is met for any kind of drug.
Gene: Protein-coding gene on chromosome 17 (41,096,981 to 41,098,142, reverse strand). Ensembl gene ENSG00000204880.
Pathways (Reactome):
Developmental Biology: Keratinization
Gene Ontology:
Biological process: hair cycle
Cellular component: cytosol; keratin filament
Genetic constraint (gnomAD): Loss-of-function variants: 1 observed, 3.06 expected, observed/expected ratio (o/e) 0.33, 90% interval 0.11 to 1.45. That is too few expected variants to judge how well the gene tolerates losing a copy. Missense variants: 187 observed, 210.34 expected, observed/expected ratio (o/e) 0.89, 90% interval 0.79 to 1. Synonymous variants: 65 observed, 70.84 expected, observed/expected ratio (o/e) 0.92, 90% interval 0.75 to 1.13.
Homologues: Orthologues: mouse Krtap5-2 (40% identical), mouse Krtap5-24 (39% identical), mouse Krtap5-26 (36% identical), rat Krtap5-8 (36% identical), rat AABR07006049.1 (35% identical), mouse Krtap5-20 (32% identical). Paralogues in human: KRTAP4-9 (91% identical), KRTAP4-11 (90% identical), KRTAP4-6 (83% identical), KRTAP4-12 (76% identical), KRTAP4-5 (71% identical), KRTAP4-7 (68% identical), KRTAP4-4 (65% identical), KRTAP4-16 (62% identical), KRTAP4-3 (59% identical), KRTAP4-2 (54% identical), KRTAP4-1 (49% identical), KRTAP10-7 (46% identical), and 35 more.